GYPE (glycophorin E (MNS blood group))
Description:
This protein is a minor sialoglycoprotein in human erythrocyte membranes.
Synonyms: GPE; MNS; MiIX
Tractability: Antibody: its Gene Ontology location is reachable by antibodies, with high confidence; UniProt predicts a signal peptide or a membrane-spanning region.
Gene: Protein-coding gene on chromosome 4 (143,870,864 to 143,905,563, reverse strand). Ensembl gene ENSG00000197465.
Subcellular location: Membrane
Gene Ontology:
Cellular component: plasma membrane; membrane
Genetic constraint (gnomAD): Loss-of-function variants: 3 observed, 6.9 expected, observed/expected ratio (o/e) 0.43, 90% interval 0.2 to 1.12. That is too few expected variants to judge how well the gene tolerates losing a copy. Missense variants: 43 observed, 44.12 expected, observed/expected ratio (o/e) 0.97, 90% interval 0.76 to 1.26. Synonymous variants: 16 observed, 15.16 expected, observed/expected ratio (o/e) 1.06, 90% interval 0.71 to 1.59.
Homologues: Orthologues: macaque GYPA (63% identical), dog GYPA (33% identical), mouse Gypa (23% identical). Paralogues in human: GYPA (72% identical), GYPB (68% identical).
Diseases named in the same sentence as GYPE in open-access papers:
GYPE is named in the same sentence as 28 diseases in open-access papers, as found by Europe PMC text mining. Sharing a sentence is not in itself a finding about the gene and the disease. The quoted sentences say what the papers report.
malaria (4 papers, 2016 to 2022). Malaria is a serious and sometimes fatal disease caused by a parasite that commonly infects a certain type of mosquito which feeds on humans. "In the remaining genomic risk loci, the well-known genes that play role in severe malaria resistance including ATP2B4 (chr1q32), FREM3, GYPE, and GYPB (chr4p31) were replicated and few additional genes were identified." (PMID 34868193, 2021).
COVID-19 (1 paper, 2021). A disease caused by infection with severe acute respiratory syndrome coronavirus 2. "Actually, some of these variants positively correlate with COVID-19 cases and increase the expression of GYPE." (PMID 33981715, 2021). "Others that negatively correlate with COVID-19 determine a reduction in the transcripts of FREM and GYPE." (PMID 33981715, 2021).
diabetes (1 paper, 2025). "These regions spanned genes (e.g., CCDC42, GYPE, MAP3K20, and OBI1) related to diseases (e.g., malaria infection and diabetes) with differing prevalence and incidence between populations." (PMID 41224710, 2025).
lung carcinoma (1 paper, 2024). "The two signatures show an overlap of four genes (EMP2, AGER, STX11, GYPE) with two of them known to be linked to lung carcinoma." (PMID 38993634, 2024).
Sepsis (1 paper, 2022). Sepsis is defined as life-threatening organ dysfunction caused by a dysregulated host response to infection. "In summary, CD81, RPL22, GYPE, and HSPB1 were screened and they are significantly associated with the immunity in sepsis-induced ARDS." (PMID 34898369, 2022).
cancer (1 paper, 2022). A tumor composed of atypical neoplastic, often pleomorphic cells that invade other tissues. "However, the blood group gene, GYPE, which belongs to the MNS antigen system, has no significance of prognostication in all cancer types." (PMID 35955933, 2022).
tumor (1 paper, 2023). "Of note, we were able to identify several hematopoiesis foci characterized by HBB and GYPE markers expression in the fibrotic area around large vessels (#3559, #4001, #3115) and in the tumor capsule (#4001) vascular area." (PMID 37932266, 2023).
GYPE also shares sentences with these, for which no sentence is quoted: Parkinson disease (5 papers); Dystonia (3); Huntington disease (2); infection (2); Parkinsonism (2); absence seizures (1); Alzheimer disease (1); basal ganglia disorder (1); cholangiocarcinoma (1); cognitive decline (1); dengue (1); epilepsy (1); Granuloma (1); hyperkinesia (1); Langer mesomelic dysplasia syndrome (1); paraganglioma (1); pheochromocytoma (1); post-traumatic stress disorder (1); prostate adenocarcinoma (1); trisomy 21 (1); ZIKV infection (1).